TIGIT (T cell immunoreceptor with Ig and ITIM domains)
Diseases named in the same sentence as TIGIT in open-access papers (continued):
Sharing a sentence is not in itself a finding about the gene and the disease.
tumor (continued). "Tumor‐infiltrating lymphocytes express multiple immune checkpoint molecules (eg, PD‐1, CTLA‐4, TIM‐3, LAG‐3, and TIGIT)." (PMID 32077528, 2020). "The novel immune checkpoint TIGIT expressed on NK cells, activated CD8+ T cells, effector CD8+ T cells and regulatory T cells (Tregs), and suppressed the anti-tumor immune response by interacting with PVR." (PMID 32894141, 2020). "TOX expression was positively correlated with the expression of various IC molecules, such as PD-1, TIM-3, and TIGIT—at protein level—in the TI CD8+ T cells isolated from both NSCLC and HNSCC tumor tissues." (PMID 32111241, 2020). "In particular, CD155 once up-regulated on different types of tumor cells is recognized by a group of receptors expressed on T and NK cells: The activating receptor DNAM-1 (CD226) and the inhibitory receptors TIGIT and TACTILE (CD96)." (PMID 32019260, 2020). "DNAM-1 has an important role in NK cell-mediated tumor immunosurveillance and shares CD155 and CD112 ligands with TIGIT and TACTILE (CD96)." (PMID 32290478, 2020). "VISTA, TIGIT and KLRG1 showed a trend towards increased expression in patients with high grades of tumor budding." (PMID 32393998, 2020). "Among these, TIGIT was found to be expressed not only on immune cells (such as CD8+ T and NK cells), but also on tumor cells, which making it a potential target for cancer immunotherapy." (PMID 32894141, 2020). "It has been proposed that in the tumor microenvironment the balance between CD155/DNAM-1 and CD155/TIGIT/CD96 contrasting signals contributes to regulate NK cell effector functions." (PMID 32019260, 2020). "In their study, triple blockade of PD-1, TIGIT, and CD96 significantly inhibited tumor growth in a B16F10 melanoma BALB/c WT mouse model." (PMID 32532329, 2020). "Together, these data suggest that TOX, and potentially TIM-3, CTLA-4, VISTA, TIGIT, KLRG1, TOX2, SIRT1, Ki-67, and Helios mRNA levels in CRC tumor tissues increase in advanced disease stages, suggesting their possible roles in CRC progression." (PMID 32393998, 2020). "In our study, we found a significant positive correlation between C10orf54 and genes such as TIM-3, TIGIT, and PDCD1LG2, which are responsible for tumor immune escape and immune suppression in human cancers." (PMID 31781843, 2020). "The known ligands for TIGIT are CD155 [also known as poliovirus receptor (PVR)] and CD112 (also known as nectin-2) that are expressed on myeloid, endothelial or tumor cells." (PMID 33117369, 2020). "Various cancers have shown upregulation of CD155 with corresponding upregulated NK and T cell expression of TIGIT and CD96 in order to evade anti-tumor immunity by eliciting T cell or NK cell inhibition." (PMID 32117298, 2020). "Second, we will discuss the expression and function of TIGIT, DNAM-1, and CD96 on lymphoid effector cells as well as tumor cells." (PMID 32489646, 2020). "Beyond PD-1, a combination of anti-TIGIT or anti-KLRG1 antibodies and DNA methyltransferase inhibitor reversed the metastasis-promoting state acquired by certain tumor-exposed NK cells." (PMID 33120910, 2020). "Several targets, such as TIGIT and BTLA, have a similar frequency of expression on CD8+ T cells in healthy donors, peripheral blood from patients with GBM, and tumor-infiltrating lymphocytes (TILs)." (PMID 32721947, 2020). "In HCC, we observed increased expression of several more activation- (IFNG, CD38, IL2RA, TNFRSF9) and exhaustion-related (TIGIT, CTLA4, PDCD1, ENTPD1) genes in tumor MAIT cells." (PMID 32849590, 2020). "The current study discovered that TIGIT, CD226, and PD-1 were all involved in the MDS-mediated tumor immune response." (PMID 32903786, 2020). "The novel immune checkpoint coinhibitory receptor T cell Ig and ITIM domain (TIGIT) shares similar ligands as the costimulatory receptor DNAX accessory molecule 1 (DNAM-1) and suppresses T cell responses in tumor patients." (PMID 32802845, 2020).
tumor (continued). "TIGIT has been shown to be up-regulated on activated CD4 T cells, including Tregs, natural killer (NK) cells, tumor antigen-specific CD8+ T cells and on NK cells where, when engaged, TIGIT directly inhibits cytotoxicity." (PMID 33117369, 2020). "Some antagonistic Abs (e.g., anti-TIGIT and anti-NKG2A monoclonal Abs) have extraordinary potential in cancer therapy, as evidenced by their induction of potent anti-tumor immunity through recovering both NK and T cell function." (PMID 32714324, 2020). "The most frequent immune targets in the CD8+ T cells from the tumor microenvironment, in descending order, of newly diagnosed patients with GBM were A2aR > PD-1 > CD39 > TIGIT > LAG-3 > CTLA- 4 > BTLA > CD160 > CD73 > KIR > TIM3." (PMID 32721947, 2020). "Tumor-infiltrating lymphocytes are in several cases found tumor-reactive, but expression of the immune checkpoint receptors TIM-3, TIGIT and LAG3 is also abundant." (PMID 32313009, 2020). "F. nucleatum mediates tumor-immune evasion via the T-cell immunoreceptor with Ig and ITIM domains (TIGIT)." (PMID 32993020, 2020). "TIGIT has been shown to bind to CD155, a coinhibitory ligand overexpressed on multiple types of malignant tumor, where it was discovered to promote tumor progression." (PMID 32903786, 2020). "In addition to the expression of CTLA-4 and PDCD1, tumor-infiltrating lymphocytes (TILs) express a number of other co-inhibitory receptors, including HAVCR2 and TIGIT, providing additional targets that could be exploited for inducing anti-tumor immune responses." (PMID 33585210, 2020). "This shift was accompanied by an upregulation of TIGIT and CD96, and concomitant reduction in DNAM-1 levels, thus creating a pro-tumor environment." (PMID 33255582, 2020). "Both TIGIT and CD96 are significantly up-regulated on chronically stimulated tumor-infiltrating NK and T cells, representing markers of exhausted cytotoxic cells." (PMID 32019260, 2020). "In conclusion, the findings of the present study demonstrated that the overexpression of TIGIT inhibited the activity of NK and T cells in patients with MDS, contributing to tumor immune escape." (PMID 32903786, 2020). "On the other hand, Tils in the tumour microenvironment, especially CD8+ T cells, also express a large number of other immune checkpoint molecules, such as LAG-3, TIM-3, TIGIT, VISTA, B7-H3, and BTLA." (PMID 32775040, 2020). "Although soluble CD155 (sCD155) contributes to the neutralization of poliovirus infectivity in vitro, it remains undetermined how it is involved in tumor immune responses mediated by DNAM-1, TIGIT, and CD96." (PMID 32040157, 2020). "It has been found that in tumor cells, immune checkpoints can lead to NK cell dysfunction, blocking these immune checkpoints (e.g. TIM-3, NKG2A, CTLA-4, PD-1, KIR2DL-1/2/3, CD96, TIGIT) can restore the function of NK cells." (PMID 33614486, 2020). "All together, this evidence demonstrates that during tumor progression the balance between DNAM-1 and its inhibitory counterparts is deregulated by an up-regulation of TIGIT and CD96, and a concomitant decrease of DNAM-1 expression." (PMID 32019260, 2020). "Tregs combined with CTLA4, LAG3, and TIGIT related to a worse prognosis in RCC exerted immunosuppressive effects, favoring tumor escape from the activity of a variety of antitumor immune effector cells." (PMID 32252440, 2020). "The competition of TIGIT and CD96 binding to DNAM-1 ligands PVR and Nectin-2 renders tumor-infiltrating NK cells exhausted." (PMID 32038612, 2019). "Up-regulation of immune checkpoint molecules (PD-1, PD-L1, CTLA-4, TIM-3, Lag-3, TIGIT, CD73, VISTA, B7-H3) in the tumor microenvironment is an important mechanism that restrains effector T cells from the anti-tumor activity." (PMID 30863404, 2019).
tumor (continued). "Initial evaluation of the anti-TIGIT mAb, OMP-31M32 (Etigilimab) in a phase Ia/b showed preclinical in vivo anti-tumor effects as a single agent and in combination with anti-PD-1 (NCT03119428) results presented at the Society for Immunotherapy of Cancer 2018)." (PMID 32039024, 2019). "TIGIT (T cell immunoglobulin and ITIM domain, also known as WUCAM or Vstm3) is a member of the CD28 family of proteins that play an important role in inhibiting T- and NK cell-mediated functional activities in anti-tumor immunity." (PMID 30863404, 2019). "Increased TIGIT and CD96 expression and lower levels of DNAM1 were also detected on ILC1s induced by TGF-β, contributing to the impairment of their anti-tumor response." (PMID 31105707, 2019). "The anti-tumor efficacy dependent on the Fc-mediated effector functions has also been demonstrated for CTLA-4, TIGIT and VISTA." (PMID 31554169, 2019). "Moreover, the transcriptional upregulation of CTLA-4 in tumor tissue might be under the control of both DNA hypomethylation and lower H3K27me3 enrichment, while DNA hypomethylation and lower H3K9me3 enrichment regulate TIGIT expression." (PMID 30081950, 2018). "This is in part due to the upregulation of several inhibitory receptors like PD-1, LAG3, TIGIT, and CTLA-4 that desensitize T cells to tumor antigens." (PMID 29482595, 2018). "Compared with the control group, depletion of CD8+ T cells completely abolished the tumor growth inhibition induced by TIGIT knockout, while CD4+ T cell depletion exhibited weaker impact on tumor growth." (PMID 30555485, 2018). "The ImmunoINTEL panels were complemented with drop-in IMR and IMR-L markers (PD1/PDL1, TIGIT/CD112-CD155, TIM-3/Galectin-9, SIRPa/CD47, LAG-3/HLADR) to profile the functional status of TILs, and to study the cytotoxic potential of tumor TILs." (PMID 30400835, 2018). "TIGIT and CD226 expression in various tumor types and normal tissues was derived from TCGA (The Cancer Genome Atlas), GTEX (Genotype-Tissue Expression Project), and immunohistochemistry." (PMID 30400822, 2018). "We have adopted this strategy and devised chimeric receptors where CD28-signaling domains were fused to the extracellular binding domains of either CD2, CD226 or TIGIT and thus can be engaged by CD58 or CD155 expressed on the tumor targets." (PMID 29707134, 2018). "Percentages of tumor infiltrating CD4+ and CD8+ T cells and the production of IFN-gamma in CD8+ T cells were significantly enhanced after anti-TIGIT antibody treatment." (PMID 30400822, 2018). "TIGIT counterbalances CD226-mediated T-cell activation by competing with CD226 for binding to PVR, a receptor that is expressed in multiple tumor types." (PMID 30400822, 2018). "Here, we discuss the interactions between PD-1, TIGIT, PVR, CD226, CD96 and CD112 and focus on how they work together to deliver immune stimulatory or inhibitory signals among tumor cells and immune cells within the TME." (PMID 29735917, 2018). "TIGIT binds two ligands, CD112 (PVRL2, nectin-2) and CD155 (PVR), and these ligands are expressed by T cells, APCs, and tumor cells." (PMID 28545567, 2017). "TIGIT has been shown to identify the most dysfunctional subset of effector CD8+ T cells in tumors, and the tumor-infiltrating Tregs characterized by a highly suppressive phenotype." (PMID 28404974, 2017). "TIGIT signaling controls Treg phenotype, and Tregs show an increased expression of TIM-3 in the tumor tissue, where TIM-3 and TIGIT synergize in the suppression of the immune responses." (PMID 28404974, 2017). "TIGIT has two ligands, namely, CD155 (poliovirus receptor, PVR) and CD112 (PVRL2) that are expressed on APC as well as on tumor cells." (PMID 29276510, 2017). "With some exceptions inflammation has been shown to repress adaptive and some innate anti-tumor responses by the direct or indirect release of soluble factors as PGE2, TGF-b, NO or by inhibitory ligands as PD-L1, CTLA4 and TIGIT." (PMID 27664151, 2017).
tumor (continued). "An inhibitory receptor found on T cells and NK cells, TIGIT acts synergistically with the PD-1/PD-L1 axis upon binding to its cognate receptor PVR, which is expressed on tumor cells or DC." (PMID 28649381, 2017). "Pathogen-specific CD8+ T cells in mouse models and humans with chronic viral infections as well as TILs from mouse tumor models and patients with cancer can coexpress multiple repressors, including PD-1, LAG-3, TIM-3, TIGIT, and others." (PMID 28443090, 2017). "For example, in the context of tumours, exhausted T cells express a whole set of inhibitory receptors with likely irredundant functions, such as CTLA4, TIM3, LAG3, TIGIT and others." (PMID 28537896, 2017). "In contrast, when TIGIT and/or CD155 upregulation predominates on immunosuppressive cell types—such as Tregs or TAMs—or on tumor cells themselves, it may reflect a more advanced state of immune escape and thus associate with poor prognosis." (PMID 41596586, 2026). "Novel inhibitory and co-stimulatory immune checkpoints such as lymphocyte activation gene-3 (LAG-3), T cell immunoglobulin mucin-3 (TIM-3), T cell immunoreceptor with Ig and ITIM domains (TIGIT), OX40, CD137 (4-1BB), and CD40 are examined for their potential to enhance anti-tumor immunity." (PMID 41832248, 2026). "Interestingly, while DC101 did not affect the infiltration of total CD8-positive T cells within the tumor, it reduced the number of exhausted CD8 T cells that were PD1-positive and TIGIT-positive." (PMID 41140754, 2026). "Notably, compared with the PD‐L1− tumor group, the upregulated differentially expressed genes (DEGs) in the CD8‐C2‐Texterm subset from PD‐L1+ tumor group included exhaustion‐related genes such as HAVCR2, CXCL13, PDCD1, TIGIT, LAG3, BATF, GNLY, and CTLA4." (PMID 41194450, 2026). "Thus, the absence of correlations with examined clinicopathological parameters in our study is in line with the notion that the clinical relevance of TIGIT and CD155 likely depends on their distribution across specific immune and tumor cell subsets." (PMID 41596586, 2026). "Collectively, these results demonstrate that TIGIT inhibition effectively restore and enhance NK cell cytotoxicity in DLBCL, potentially reversing tumor-mediated immune suppression and augmenting anti-tumor immunity." (PMID 40231264, 2025). "Pulmonary commensal bacteria—particularly taxa enriched in tumor tissue—may chronically stimulate NK cells in TME, resulting in increased TIGIT expression on NK cells and upregulated expression of the ligand CD155 on tumor cells." (PMID 41516132, 2025). "Notably, several of these checkpoints (e.g., PDCD1, LAG3, TIGIT and CTLA4) collectively impair T cell function through distinct mechanisms, driving immune evasion and tumor progression." (PMID 41562077, 2025). "However, this balance can be disrupted within the tumor microenvironment, where inhibitory signaling predominates due to decreased CD226 and increased TIGIT expression." (PMID 40411696, 2025). "As an IC receptor within the IgSF, TIGIT interacts with ligands such as CD155 (PVR or Nectin-5), CD113 (PVRL3 or Nectin-3), CD112 (PVRL2 or Nectin-2) and PVRL4 (Nectin-4) to suppress T cell activity, facilitating tumour evasion of immune surveillance." (PMID 40994140, 2025). "Our results indicated a significant increase in CD4 + and CD8 + T cells in the tumour micro-environment, rather than peripherally following treatment with anti-PD-1 and anti-TIGIT." (PMID 39939955, 2025). "On the other hand, the interaction between TIGIT and CD226 attenuates immune operations, while nectin-2 and nectin-4 are identified as promising targets in cancer treatment due to their effects on the behavior of tumor cells." (PMID 40777027, 2025). "TIGIT+ CD8+ T cells exhibit reduced levels of effector molecules such as IFN-γ, perforin, and granzyme B, indicating functional impairment and supporting TIGIT’s role in promoting T cell exhaustion within the tumor microenvironment." (PMID 41300994, 2025).
tumor (continued). "Blocking TIM-3, LAG-3, and TIGIT can synergize with PD-1 blockade to restore the proliferative capacity of exhausted CD8+ T cells in tumors and upregulate NK cell activation, thereby enhancing tumor-killing effects." (PMID 40821806, 2025). "Like tumor cells and FDCs, CAFs also express CD155 and CD112, engaging TIGIT on TILs." (PMID 41268548, 2025). "The T cell Immune-receptor with immune-globulin and ITIM domain (TIGIT) is a coinhibitory immune-modulatory checkpoint receptor, present on T cells CD8+, CD4+, T regs, and NK cells, which binds to ligands CD112 and CD115 on tumor cells and APCs." (PMID 41514645, 2025). "TIGIT competes with the activating receptor CD226 for binding to CD155, which results in a reduction of NK cell cytotoxicity and T cell activation, thus hindering effective anti-tumor immune responses." (PMID 39941737, 2025). "CRISPR/Cas9-mediated TIGIT knockout may impair CAR-T fitness, as evidenced by faster tumor growth in the EC-CART group compared to the CART+IgG group." (PMID 41419632, 2025). "Recent mechanistic studies show that combined blockade of PD-1 and TIGIT expands tumour-reactive CD8+ T-cell clones and restores effector function, supporting the rational design of triplet regimens (e.g. PD-1 + IL-33/ST2 + TIGIT) in biomarker-selected cohorts." (PMID 41284319, 2025). "Preclinical studies demonstrate that TIGIT, LAG-3, and CTLA-4 contribute to T-cell exhaustion through distinct mechanisms, and their co-blockade enhances CD8+ T-cell responses, reduces Treg-mediated immunosuppression, and delays tumor growth in murine models." (PMID 40567374, 2025). "The TIGIT protein is overexpressed on immune cells, such as CD4+ and CD8+ T cells, but also natural killer (NK) cells, having an essential role in immunosuppression, especially through interaction with the tumor microenvironment (TME)." (PMID 40277786, 2025). "We uncovered a novel mechanism of tumor escape from ILC2-mediated immune surveillance, providing further rationale for the clinical employment of anti-TIGIT mAb in the treatment of these pts, and, potentially, in the earlier stages of MM too, with the aim of slowing down disease progression." (PMID 39858045, 2025). "TIGIT binds primarily to the CD155 receptor, also known as the polio virus receptor (PVR), which is expressed on monocytes, dendritic cells (DCs), fibroblasts, endothelial cells, and tumor cells from many cancers." (PMID 40075753, 2025). "Tumor sections were stained with checkpoint markers: PD1, CTLA4, LAG3, TIGIT, and TIM3." (PMID 40067762, 2025). "This review systematically elucidates the expression profiles, signaling pathways, and the immune checkpoint molecule regulatory mechanisms localized on the NK cell membrane (e.g., NKG2A, KIRs, and TIGIT) or intracellularly (e.g., BIM, Cbl-b, and EZH2) during tumor immune evasion." (PMID 40463500, 2025). "They drive NKs exhaustion and facilitate tumor immune escape by depleting activation factors like IL-2, releasing immunosuppressive molecules such as TGF-β and IL-10, and activating inhibitory receptors on NK cells, including PD-1 and TIGIT." (PMID 40008144, 2025). "Moreover, first functional evaluation proofed that blockade of TIGIT and/or PVRIG prevented NK cell exhaustion and promotes NK cell–dependent tumor immunity in solid and hematological tumor models." (PMID 40274631, 2025). "PD-1 and LAG-3 double knockout CD8+ T cells exhibit higher TCR diversity, stronger cytotoxicity (increased expression of GZMB and PRF1), and IFN-γ dependent anti-tumor effects, while the combination of PD-1 with TIM-3 or TIGIT blockade is still in the exploratory stage." (PMID 40821806, 2025). "Lack of TIGIT expression or blocking of TIGIT specifically in NK cells using antibodies, retarded tumor growth and reversed antitumor NK cell exhaustion." (PMID 40236693, 2025).